PPM1D (protein phosphatase, Mg2+/Mn2+ dependent 1D)
Diseases named in the same sentence as PPM1D in open-access papers (continued):
Sharing a sentence is not in itself a finding about the gene and the disease.
cancer (continued). "Transcriptional profiling of such a large cohort of a single molecular type of cancer allows for a thorough understanding of the tumor’s genomic landscape, including the identification of genes affected by mutations (GNAS, MYCN, PPM1D, and PRKAR1A), and fusion transcripts (ZBTB20 and NCOR1)." (PMID 33741928, 2021). "The analysis demonstrated that PPM1D expression was significantly upregulated in most cancers." (PMID 34470916, 2021). "We hypothesized that continued proliferation in the presence of genotoxic stress may lead to genome instability and promote cancer development in animals carrying truncated Ppm1d." (PMID 32927737, 2020). "In addition, high expression of PPM1D can also affect response to therapy as it reduces the sensitivity of cancer cells to doxorubicin and other chemotherapeutics." (PMID 32927737, 2020). "In contrast, it has also been reported that PPM1D mosaic truncating mutations in the blood have been associated with chemotherapy rather than predisposition to the cancers." (PMID 31242196, 2019). "The highest response is observed in cancer cells with the amplified PPM1D (such as MCF7) or truncated WIP1 (such as U2OS), suggesting that these cells might be addicted to the high level of WIP1." (PMID 28439615, 2017). "Our findings therefore suggest that PPM1D is an attractive future target for cancer therapy." (PMID 27619510, 2016). "Thus, given PPM1D’s overexpression in most carcinomas and its various targets, it is likely to be involved in various important processes in cancer cells." (PMID 27619510, 2016). "First, it is currently unknown if gene amplification of PPM1D occur in ATL as observed in other types of cancers." (PMID 23256570, 2012). "In non-luminal HER2-positive cancer, PPM1D overexpression was associated with worse OS." (PMID 41465262, 2025). "PPM1D may serve as a suitable model substrate for elucidating the mechanism of ubiquitin-independent proteasomal degradation and represents a potential novel therapeutic target for cancer treatment based on proteasome inhibition." (PMID 40931354, 2025). "Thus, it is of no surprise that somatic PPM1D gain-of-function mutations have also been implicated in cancer, including breast and colon cancer." (PMID 36313552, 2022). "Furthermore, mapping of the phosphoproteome induced by etoposide and PPM1D inhibition may provide insights into the mechanisms driving the positive selection of cancer cells with PPM1D amplification." (PMID 36060052, 2022). "However, the expression of PPM1D differed in various cancers." (PMID 34470916, 2021). "In addition, an increased STC1 expression level after protein phosphatase magnesium‐dependent 1 delta (PPM1D) silencing indicated that STC1 was affected by PPM1D, a protein overexpressed in various cancer cell lines, which has been associated with poor prognoses of cancers." (PMID 32468698, 2020).
cancer (continued). "In this context, somatic PPM1D mutations could be a result of expansion of a PPM1D-mutated clone under selective pressure by cisplatin chemotherapy, rather than a risk factor or cause of the respective cancers." (PMID 31242196, 2019). "Since cancer cells are genetically instable, we tested whether PPM1D truncation would cause similar defects in non-transformed cells." (PMID 31659152, 2019). "Similar to the NSCLC validation cohort, patients with TET2-mutant CHIP from the pan-cancer cohort had the highest frequency of TI-CH (33%, 381/1191), followed by ASXL1-mutant (32%, 124/392), DNMT3A-mutant (25%, 926/3,753), and PPM1D-mutant CHIP (13%, 83/622)." (PMID 40267425, 2025). "The majority of the 39 monogenic rare variant containing genes are either well-known tumor suppressors or suspected to have a tumor suppressor role, whereas only PPM1D and ERBB2 are classified as bonafide oncogenes by the Cancer Gene Census." (PMID 34755241, 2022). "In the past decade, several isoform specific inhibitors have been reported, mostly targeting PPM1A, PPM1D, PHLPP1/2 and PPM1E/F isoforms and have been tested as potential cancer therapy." (PMID 34091011, 2021). "This chromosomal region contains several genes connected to cancers including EME1, BRCA1, ERBB2, NF1, RAD51C, BRIP1, BIRC5 and PPM1D." (PMID 34885154, 2021). "Besides, they implied that PPM1D could be a potential prognostic biomarker for cancer progression." (PMID 34470916, 2021). "Although GSK2830371 is a weak inhibitor of proliferation on different cancer cell lines, it dramatically potentiates the effect of MDM2 inhibitors, especially in cells where there is a WIP1/PPM1D overexpression or hyperactivation." (PMID 30689917, 2019). "To test the sensitivity in cancer cells, we used HCT116 cells that intrinsically carry PPM1D truncation, and exposed them to 5-FU, a chemotherapeutic agent commonly used in CRC treatment." (PMID 31659152, 2019). "The PPM1D gene (also known as WIP1) maps to the 17q23.2 amplicon and is amplified and/or overexpressed in various types of cancers, including CCC." (PMID 25366985, 2014).
cancer (continued). "Understanding the molecular biology of WIP1 inhibitors could increase the potency of WIP1 inhibitors in a specific subsets of tumors with PPM1D/RPS6KB1 and ERBB2 co-amplification that may lead to improved cancer care." (PMID 31827209, 2019). "Of the 186 patients without germline P/LP variants and available cancer genomes–exomes, 41/186 patients had a somatic variant in the DNA damage response pathway (ATRX, ATM, PPM1D, POLE) and 21/186 had a variant in the MAPK-ERK pathway (BRAF, NF1, PTPN11, MAPK12)." (PMID 40072012, 2025). "Using PPM1D as an example of a classical member of the PP2C family, we will describe how phosphatases of this family regulate different forms of cell death and why they have become a promising target in the treatment of various diseases, including cancer therapy." (PMID 39702569, 2024). "This study focuses on the identification of PPM1D substrates in cancer cells expressing hyperactive PPM1D and thus we do not exclude the possibility that the substrate spectrum of PPM1D in these cells is altered compared to cells expressing the wild-type protein." (PMID 36060052, 2022). "WIP1 (PPM1D) has a significant anti-apoptotic effect on uLMS, whereas BCL2 or MCL-1 appear to play little or no role in this cancer cell type." (PMID 35008180, 2021).
tumor (120 papers, 2007 to 2025). "Together, these findings suggest that the presence of a Ppm1d mutation affects the tumor cell state and cell cycle status of tumor cells." (PMID 41394550, 2025). "A Cre-inducible knockout model further linked Ppm1d loss in hematopoietic cells to suppressed tumor growth." (PMID 41394550, 2025). "In this study, we developed a conditional mouse Ppm1d allele to study the impact of DMG-derived PPM1D truncations on tumor development, progression and treatment response." (PMID 41394550, 2025). "Alternatively, PPM1D can be stabilized in tumor cells by mutations in the regulatory domain, which, similar to amplification of the gene, affects tumorigenesis and resistance to anticancer therapy." (PMID 39702569, 2024). "Conversely, patients with baseline wildtype PPM1D experienced greater best-response tumour size reductions than those with PPM1D mutations (p = 0.048)." (PMID 36583171, 2022). "In our analysis, the presence and accumulation of PPM1D mutations appeared to correlate with poorer tumour responses." (PMID 36583171, 2022). "Correspondingly, tumor-associated neutrophils (TANs) isolated from B16F10 tumors engrafted in Ppm1dKO2/KO2 mice compared with Ppm1d+/+ mice exhibited significantly increased survival during TCM culturing." (PMID 34131120, 2021). "Other studies have shown that overexpression of PPM1D together with oncogenes augmented tumor formation in mice or resulted in reduced the survival of mice deficient of the APC tumor-suppressor gene." (PMID 34771656, 2021). "PPM1D “gain-of-function” mutations provide selective advantage in tumor cells and in the hematopoietic system, resulting in therapy-induced CH40,80." (PMID 34131120, 2021). "For the patients with PPM1D mutations in blood, tumor tissue specimens were examined for the PPM1D mutation using conventional sequencing." (PMID 31242196, 2019). "The results of the present study showed an association of high PPM1D mRNA expression with more aggressive tumor behaviors, including higher α-FP level, advanced TNM stage and higher recurrence incidence." (PMID 23556002, 2013).
tumor (continued). "Besides, PPM1D mRNA expression indicated a positive correlation with tumor-infiltrating Monocytes, tumor-associated macrophages (TAMs), M1 Macrophage, M2 Macrophage, dendritic cells (DCs), T-helper (Th) and Treg." (PMID 34470916, 2021). "We suggest the tumor-promoting role of truncated PPM1D may be related to some mutational signature that differs between small intestinal and colon tissue." (PMID 31659152, 2019). "Finally, we searched the COSMIC database and found that PPM1D truncations in exon 6 harbor 89% of all PPM1D mutations (166/186) identified in various tumor types." (PMID 31659152, 2019). "These include RPS6KB1, APPBP2, and PPM1D that also showed strong association between amplification and increased expression in our primary tumour material." (PMID 17353917, 2007). "Additionally, several factors influence the effectiveness of CAR T-cell therapy, including a pro-inflammatory state, the tumor microenvironment, PPM1D mutations, single nucleotide polymorphisms in the cluster of differentiation 19 (CD19) antigens, and circulating monocytes." (PMID 39822464, 2024). "This study describes a novel mouse model that provides a powerful platform to investigate PPM1D-driven tumor biology and offers mechanistic insights into disease development and progression." (PMID 41394550, 2025). "Recent advancements have also highlighted the potential of selective PPM1D inhibition as a promising anticancer strategy, either by delaying tumorigenesis or reducing tumor burden." (PMID 40104406, 2025). "The authors delineate the role of PPM1D in tumor cell transformation by regulating senescence and cell death." (PMID 39702569, 2024). "Further, we show that increased PPM1D activity promotes cell growth in the soft agar and formation of tumours in xenograft models." (PMID 39237765, 2024). "NAPRT-negative tumours usually present with mutations in isocitrate dehydrogenase 1 and 2 (IDH1/2) and protein phosphatase 1D (PPM1D)." (PMID 36078035, 2022). "Among the DEGs that fell into this group, there were tumor-associated genes such as GADD45A, PPM1D, PLK2 and CREBRF." (PMID 35682850, 2022). "The Sangerbox, TIMER, GEPIA, and Kaplan-Meier Plotter databases were used to study the status of PPM1D mRNA in tumor tissue." (PMID 34470916, 2021). "Compared with Ppm1d mRNA levels in BM neutrophils from tumor-free WT mice, Ppm1d mRNA levels were significantly increased both in BM neutrophils from tumor-bearing mice and in TANs." (PMID 34131120, 2021). "To investigate the effects on tumor progression of reducing Wip1 expression in immune cells, we established mouse lines with conditional knockout of the Ppm1d gene." (PMID 34131120, 2021). "Irradiated transgenic mice carrying the PPM1D gene had significantly higher tumor incidence (34% tumor probability) compared to wild-type mice (7.8%; p < 0.0001) 100–300 days post-irradiation." (PMID 34771656, 2021).